INS (insulin)
Diseases named in the same sentence as INS in open-access papers (continued):
Sharing a sentence is not in itself a finding about the gene and the disease.
endocrine disorder (129 papers, 2005 to 2025). "In the context of endocrine disorders, molecular therapy is particularly effective in modulating pathogenic mechanisms such as defective insulin signaling, beta-cell dysfunction and hormonal imbalances." (PMID 39944202, 2025). "Equine metabolic syndrome (EMS) is a prevalent endocrine disorder associated with insulin dysregulation, oxidative stress, and impaired regenerative capacity of adipose-derived stem cells (ASCs)." (PMID 40725115, 2025). "Different breeds of horses and ponies have been involved in corticosteroid-induced laminitis cases, which are usually associated with underlying endocrinopathies, especially insulin dysregulation." (PMID 40362130, 2025). "DM is an endocrine disorder that is caused by insufficient production of insulin or by improperly functioning insulin signaling that affects glucose tolerance as well as the metabolism of carbohydrates, proteins, and fats." (PMID 37398721, 2023). "T2DM is an endocrine disease caused by defective insulin secretion and decreased function in regulating glucose metabolism, manifesting as chronic hyperglycemia and nutrient metabolism disorder." (PMID 36003504, 2022). "DM is an endocrine disorder caused by inherited and/or acquired deficiency in the amount of insulin from the pancreas, or by the defects in insulin action." (PMID 27809221, 2016). "We might include patients with a history of endocrine disorders, which could be associated with insulin or GLP- 1R expression." (PMID 40281248, 2025). "In addition, hunger, cold, exogenous diet stimulation, endocrine diseases, and the selection of inspection methods and reagents could potentially have caused an abnormal secretion of insulin." (PMID 29445549, 2017). "Given the prevalence of endocrine diseases within older sport horse types, it would be prudent to rule out the presence of any endocrine disorder and especially insulin dysregulation, with appropriate testing, prior to use of corticosteroids." (PMID 40362130, 2025). "This endocrine disorder stems from inadequate insulin production by the pancreas or the body's inefficiency in utilizing insulin effectively." (PMID 38465169, 2024). "This endocrine disorder results from either insufficient pancreatic production of insulin or the body's inefficient use of insulin." (PMID 38465169, 2024). "The measurement of the blood insulin concentration, and comparison to cut-offs, is essential in diagnosing insulin dysregulation, a common equine endocrinopathy." (PMID 37684968, 2023). "The imbalance of blood sugar absorption, insulin secretion, and insulin action can be seen as the common results of this endocrine disease." (PMID 37720866, 2023). "The diabetic disease is an endocrine disease characterized by an increased rate of serum glucose due to defects in insulin secretion, insulin action or both conditions." (PMID 36135647, 2022). "In the veterinary field, canine DM is a common endocrine disease, and currently, the only available treatment option for canine DM is insulin injection throughout life." (PMID 33133196, 2020). "All these factors impair insulin signaling, which is a major component of endocrine disorders, including EMS." (PMID 29316632, 2018). "Endocrine disorders, including abnormal biological response of cells to normal insulin concentrations, are among the most common complications." (PMID 27212946, 2016). "Concerning molecular genetic studies, PCOS is one of the most extensively studied endocrinopathys in women, and attention has been given to insulin resistance, with special focus on the INSR gene, with uncertain results." (PMID 21645371, 2011). "After NaBu treatment, T, LH and INS were significantly lower while E2 and P4 were significantly higher, suggesting that NaBu treatment could reverse endocrine disorders in PCOS rats." (PMID 40704148, 2025).
endocrine disorder (continued). "Furthermore, liquids empty faster from the stomach and are absorbed more quickly in the intestine, leading to increased insulin release and endocrine disorders, ultimately increasing Denovo TG synthesis." (PMID 38408923, 2024). "Other mechanisms include damage to the vascular endothelium due to oxidative stress, altered coagulation status due to fluctuations in the expression levels of coagulation factors, and imbalance in the levels of insulin and leptin secretion due to endocrine disorders." (PMID 39464793, 2024). "Specific factors that intervene to favor this imbalance are metabolic acidosis, endocrine disorders involving the insulin/IGF-1 signaling, low testosterone levels, alterations in the renin–angiotensin–aldosterone system, systemic inflammation, and an abnormal hypothalamic appetite regulation." (PMID 34383112, 2022). "This lignan may be also a beneficial agent in the treatment of endocrine disorders connected with disturbed insulin homeostasis such as PCOS." (PMID 34576213, 2021). "Metformin, which has insulin-lowering effects by ameliorating insulin sensitivity in liver and peripheral tissues, is the most widely used drug for regulating metabolic and endocrine disorders in PCOS, and it can, in turn, improve ovarian steroidogenesis and decrease circulating androgen level." (PMID 32490533, 2020). "Although there have been many studies on the pathogenesis and pathological mechanisms of EHT, including endocrine system disorders, vascular endothelial cell dysfunction, nervous system dysfunction, oxidative stress, insulin resistance, etc., the specific mechanism remains unclear." (PMID 38911515, 2024). "It has been reported in subsequent studies that metaplasia of tendon fibers, differentiation of tendon stem cells into chondrocytes and osteoblasts, endocrine disorders (thyroxine, estrogen, insulin), and genetic factors may also be related to the development of CaT." (PMID 35135484, 2022). "Various therapeutic approaches have been attempted in PCOS, including supplementation with inositols, MI and DCI, which may have distinct and synergic physiologic roles in the metabolism of glucose and in the regulation of insulin action, counteracting the endocrine disorder of this syndrome." (PMID 28642705, 2017). "ICI-related DM, like other ICI-related endocrinopathies, is not reversible and therefore requires lifelong insulin therapy." (PMID 39518461, 2024). "Our study showed that insulin-deficient diabetes mellitus has gradually increased and is no longer an infrequent ICI-related endocrinopathy, which is different from prior literature reports." (PMID 32507965, 2020). "Our results showed that MET treatment decreased serum insulin, testosterone, E2, and LH levels and promoted the secretion of FSH in PCOS rats, while DOP treatment showed similar effects to MET, indicating that DOP has the effect of improving endocrine disorder in PCOS rats." (PMID 35992123, 2022). "Further evaluation of the role of FA proteins in cellular processes involving intracellular vesicles, such as autophagy and insulin secretory pathways, could shed light on non-canonical functions of these proteins that contribute to the endocrinopathies in FA patients." (PMID 31461451, 2019).
neurological disorders (76 papers, 2009 to 2026). "Although the protective mechanisms are currently unclear, there are known roles for GLP-1 and insulin signaling in PD and other neurological disease risk." (PMID 40569082, 2025). "As impairment in the insulin signal transduction pathway has been pinpointed as a distinguished hallmark of neurological disorders, recent research has focused on formulation strategies to re-sensitize the signalling pathway." (PMID 38441832, 2024). "Changes in brain insulin and IGF1 signaling have been associated with neurological diseases, however the molecular factors regulating brain insulin sensitivity remain uncertain." (PMID 37463909, 2023). "Insulin alterations and changes in glucose metabolism were suggested to be risk factors for developing certain neurological diseases." (PMID 35615716, 2022). "This review remarks on the significance of insulin and brain glucose metabolism alterations as keystone common pathogenic substrates for certain neurological diseases, highlighting new potential targets." (PMID 35615716, 2022). "Insulin desensitization, therefore, can enhance the risk of developing neurological disorders in later life." (PMID 31068799, 2019). "The prevention of neurological diseases by IF might mainly be the result of the effects IF has on weight loss and insulin sensitivity in obese subjects." (PMID 34579042, 2021). "Therefore, the neurological diseases associated with T1-DM and T2-DM are different, especially in relation to insulin." (PMID 24319479, 2013). "Reduced systemic inflammation, increased energy expenditure, improved insulin sensitivity, satiety stimulation, mitochondrial function, blood pressure reduction, appetite suppression, and improved cognitive function from a variety of neurologic diseases are all caused by SCFAs." (PMID 40650200, 2025). "The interaction of S1P with S1PR2 and peripheral insulin resistance after conversion into Cer could also affect the brain through the pancreatic axis, inducing insulin resistance of neurons and increasing the risk of neurological diseases." (PMID 37867511, 2023). "Reasonable physical exercise can provide a valuable means of inhibiting inflammation and microglial activation, with confirmatory indicating that exercise can prevent and treat neurological diseases by inhibiting inflammation-mediated insulin resistance." (PMID 38818523, 2024). "Brain glucose hypometabolism and insulin alterations are common features of many neurological diseases." (PMID 39170185, 2024). "The disruption of the barrier did not induce any cytotoxic effects or alter the localisation pattern of claudin-1, -4, -7 and occludin, suggesting its therapeutic potential and use in intranasal insulin therapy for neurological disorders such as AD." (PMID 38441832, 2024). "According to these results, exercise effectively improves insulin resistance in the central nervous system and significantly positively affects learning, cognition, and prevention of neurological diseases." (PMID 38818523, 2024). "The beneficial effects of nasally administered insulin in the CNS have prompted researchers to examine its effects in managing neurological disorders." (PMID 38441832, 2024). "Accordingly, it is crucial, for scientific, health, economic and social reasons, to gain further insights into brain glucose metabolism and central insulin signaling in neurological disorders." (PMID 35615716, 2022). "Insulin resistant persons often experience a depressed mood resulting from neurological disorders and fluctuations of glucose and insulin concentrations at the neural level." (PMID 36613051, 2022). "Insulin’s therapeutic effect on astrocyte viability, physiology, and function in the context of neurological disorder and neurodegeneration is starting to garner interest and represents a novel avenue for theraputic intervention." (PMID 33100956, 2020).
neurological disorders (continued). "Insulin is increasingly being used as a therapeutic in pre-clinical and clinical studies of neurological disorders due to its ability to provide neuroprotection, increase synaptogenesis, improve learning and memory, and positively regulate energy homeostasis." (PMID 30796294, 2019). "We recently reported that insulin-dependent inhibition of GSK3β, a kinase with a growing list of neurologic disease links, phosphorylates dynein and regulates its interactions with Ndel1 and APC." (PMID 29404402, 2018). "In terms of target indications, the endocrine, metabolic and genetic drugs repurposed into CNS have all been, apart from one new indication of insulin, repurposed within neurological disorders." (PMID 28473889, 2017). "Furthermore, insulin intervention in the peripheral and central nervous systems of rats and mice can significantly alleviate neurological diseases, with insulin signaling activation as a potential molecular mechanism." (PMID 38818523, 2024). "These benefits include weight loss, liver enzymes and biomarkers improvements, optimal glucose homeostasis due to insulin and glucagon in the pancreas, less incidence of cardiopulmonary-related and neurological diseases, cardioprotective effects, and reductions in blood pressure." (PMID 36819350, 2023). "Hence, our study demonstrated that Pd@insulin clusters are promising nanodrugs for the treatment of TBI and other ROS-related neurological disorders." (PMID 35752849, 2022). "Recently, two patients with mutations in IREB2 have been identified that exhibit early onset and progressive neurological disease, and microcytic anemia; however, insulin sensitivity and secretion were not reported for these patients." (PMID 31941883, 2020). "As in vivo studies have demonstrated the neuroprotective actions of insulin in ameliorating 6-OHDA-induced motor behavioural impairments, the therapeutic potential of nasally administered insulin should be further explored in different neurological disorders such as PD and neuronal injury." (PMID 38441832, 2024). "The effects of IF on neurological disease prevention might lie in improving metabolic markers such as insulin sensitivity, which is not or less applicable to non-obese subjects." (PMID 34579042, 2021).
psychiatric disorder (75 papers, 2009 to 2026). A disorder characterized by behavioral and/or psychological abnormalities, often accompanied by physical symptoms. "Use of insulin injections, diabetic microangiopathy, and psychiatric disorders were associated with worsened glycemic control after discharge." (PMID 37396672, 2023). "Among those, antidiabetic drugs (non-insulin) use was associated with a 30% reduction in probability of having some common psychiatric disorder (OR = 0.70; 95%CI:0.34–1.43, p = 0.32), but the result was not statistically significant." (PMID 36342534, 2023). "A physically inactive lifestyle may be a key risk element for mental illness, as continuous inactive time appears to decrease and impair insulin tolerance modifications, glucose homeostasis, and plasma triglyceride levels, which could consequently affect one's frame of mind and happiness." (PMID 36727085, 2022). "The most studied compounds included curcumin, quercetin, carbamazepine, diazepam, and insulin, each with therapeutic applications in neurodegenerative and psychiatric disorders." (PMID 41012443, 2025). "A systematic approach for assessing psychiatric disorders in patients manipulating insulin therapy is strongly advocated." (PMID 38442115, 2024). "Exclusion criteria were: unable to speak Swedish, untreated or severe psychiatric disease, cortisone treatment, untreated thyroid disease and newly started insulin pump therapy." (PMID 38101850, 2023). "Our results imply that altered insulin signaling is not only relevant for somatic disorders but is also involved in the etiology of psychiatric disorders and related symptoms in the population, especially OCD and OCS." (PMID 32341337, 2020). "For more severe psychiatric disorders, treatments supplemented with these particles through the use of a medical infusion device akin to an insulin pump could be envisaged." (PMID 39471185, 2024). "A high proportion of the GDM-Insulin group had past/current mental illness (60%)." (PMID 36733299, 2023). "Intentional skipping of insulin doses due to fear of gaining weight, higher prevalence of eating, and psychiatric disorders may lead to poor disease control, which could explain the higher incidence and younger age in the female subset." (PMID 35673321, 2022). "Given the importance of glycaemic regulation in the brain, and the direct significance of insulin signalling, these data suggest that dysglycaemia may be involved in the pathogenesis of psychiatric disorders." (PMID 32920595, 2021). "In the current study, our findings suggest that psychiatric disorders may affect peripheral insulin sensitivity, possibly via behavioral and/or neuroendocrinologic pathways." (PMID 29789273, 2018). "Thus, in comparison to the GDM-Diet group, the GDM-Insulin group had a greater proportion of women with a history of mental illness requiring medication (60% vs 15%, P = 0.006), more of whom continued to take this medication throughout their pregnancy (27% vs 0%, P = 0.026)." (PMID 36733299, 2023). "A recent post-mortem analysis in the brain of patients diagnosed with mental illness has observed a correlation between gene expression of proteins involved with both the dopaminergic system and the insulin signaling, supporting the idea that insulin could regulate the dopaminergic response." (PMID 30837902, 2019). "The specific association between HbA1c and psychiatric disorders was investigated using multiple linear regression, which confirmed a statistically significant association (p = 0.027), independent of other factors such as insulin dose, BMI, and SGLT-2i treatment." (PMID 39853629, 2025). "In contrast to women with GDM treated with insulin, women with GDM treated with diet had relatively low rates of past or current mental illness." (PMID 36733299, 2023). "An unexpected finding was that women with GDM requiring insulin, but not women with diet-treated GDM, had a high risk of mental illness prior to pregnancy." (PMID 36733299, 2023).
psychiatric disorder (continued). "Moreover, in women with a history of mental illness, care should be taken to ensure that they undergo the recommended screening tests for GDM and have appropriate follow-up, as a diagnosis of GDM in this setting may be associated with an increased likelihood of requiring insulin." (PMID 36733299, 2023). "Cases used significantly more insulin, glucagon-like peptide-1 (GLP-1) receptor analogs, antibiotics, steroids (systemic and local), opioids, non-steroidal anti-inflammatory agents (NSAIDs), and medications for respiratory, cardiac, gastrointestinal, and psychiatric disorders." (PMID 41517451, 2025). "Furthermore, when applying insulin therapy in patients with psychiatric disorders, psychotic patients required higher doses of insulin compared to non-psychotic subjects, indicating some degree of insulin resistance." (PMID 25477781, 2014).